TTN (titin)
Diseases named in the same sentence as TTN in open-access papers (continued):
Sharing a sentence is not in itself a finding about the gene and the disease.
thymoma (continued). "Significant differences were found among MGFA subtypes in relation to AChR (p < 0.001), MuSK (p < 0.001), titin (p < 0.001), disease complications (p < 0.001), thymoma (p < 0.001), and hypertension (p = 0.041)." (PMID 39968461, 2025). "Among MGFA subtypes, significant differences were detected in AChR, MuSK, titin, complications, thymoma, and hypertension." (PMID 39968461, 2025). "A diagnosis of ectopic thymoma with paraneoplastic myasthenia gravis was supported by positive anti-acetylcholine receptor and anti-titin serum antibodies." (PMID 39574984, 2024). "In particular, anti-titin was found in 80% of patients with MG and thymoma, especially in patients younger than 60-year-old." (PMID 39555481, 2024). "Titin antibodies are an important biomarker for the presence of thymoma in MG, i.e., for the instruction of thymectomy operation, as well as for diagnosis and prognosis of severe MG disease." (PMID 36830985, 2023). "The small sample size of the histological tumor subgroups did not allow us to draw definitive conclusions on the relationship between muscle/muscle-like autoantigen expression and autoantibody (anti-RYR1 and anti-TTN) profile in thymoma patients." (PMID 36979710, 2023). "RYR1 and TTN epitopes, along with costimulatory molecules, were detected in neoplastic thymoma cells, suggesting a primary autosensitization to these autoantigens in the neoplastic thymic tissue." (PMID 36979710, 2023). "Generally, the presence of anti-titin antibodies in MG patient sera is related to age and to the presence of thymoma." (PMID 36830985, 2023). "Titin and ryanodine receptor Abs always coincide with AChR-MG and are present in high frequency in thymoma." (PMID 37781409, 2023). "Anti-TTN antibodies were detected in the serum from 9 out of 17 thymoma MG patients, including 4 out of 6 patients with type A/AB, 2 out of 5 patients with type B1/B2, and 3 out of 6 patients with type B3/B3 mixed thymoma." (PMID 36979710, 2023). "Several early studies have searched for evidence of an altered expression of the AChR-α subunit in MG thymuses; RYR1 and TTN expression was also widely investigated in MG thymomas." (PMID 36979710, 2023). "Routine imaging should follow with a chest computed tomography to screen for thymomas if the specific anti-titin and anti-ryanodine receptor (anti-RyR) muscle antibodies are positive and myasthenia gravis is suspected." (PMID 36968847, 2023). "It is highly likely that the presence of thymoma in AChR+Titin-MG patients is related to their disease pathology." (PMID 35614931, 2022). "As shown in other research on PNS, the common antibodies and tumours were anti-Yo, anti-Hu, and anti-titin antibodies and thymoma and lung cancers, respectivel y, which were partially consistent with our study." (PMID 34872566, 2021). "A lower risk for autoimmune comorbidity has also been demonstrated in patients with muscle antibodies against titin and ryanodine receptor, which predicts the presence of thymoma in patients with MG." (PMID 34880829, 2021). "In EOMG patients titin antibodies are a strong indication for the presence of thymoma, as they are found in 50–95% of EOMG patients with thymoma, but only in few non-thymoma EOMG patients." (PMID 32117321, 2020). "The detection of antibodies against intracellular antigens, has proven invaluable as markers of disease severity, or identification of comorbidities, such as titin antibody detection for thymoma in EOMG." (PMID 33329350, 2020). "Approximately 70% of cases of thymoma in patients with MG have titin and ryanodine receptor (RyR) antibodies." (PMID 30823884, 2019). "Autoreactive T cells that are specific for AChR and titin are found in the sera of thymoma patients and thymoma patients with MG." (PMID 24959269, 2014). "Striational antibodies, which react with epitopes on the muscle proteins titin, ryanodine receptor (RyR), and Kv1.4, are frequently found in MG patients with late onset and thymoma." (PMID 22312479, 2011).
thymoma (continued). "Additional non-AChR muscle autoantibodies reacting with striated muscle titin and RyR antigens are found in up to 95% of MG patients with a thymoma and in 50% of late-onset MG patients (MG onset at age of 50 years or later)." (PMID 21860784, 2011). "Autoreactive T cells specific for AChR and titin are found both in thymomas and in thymoma MG patients' sera." (PMID 21860784, 2011). "Thymoma MG and late-onset MG share similar serological profile with high prevalence of titin and RyR antibodies and lower AChR antibody concentrations compared to early-onset MG." (PMID 21860784, 2011). "Titin and RyR antibodies and radiological examination of the anterior mediastinum share similar sensitivity for the presence of a thymoma in MG." (PMID 21860784, 2011). "In addition, some MG cases have autoantibodies against striated muscle antigens, titin, and ryanodine receptor (RyR), mainly detected in serum samples from patients with thymoma and late-onset MG." (PMID 39968461, 2025). "Positivity for both RyR and titin suggested a high likelihood of thymoma with a poor prognosis." (PMID 39968461, 2025). "This applies independently of the groups of patients with titin antibodies, including MG patients with thymoma, hyperplastic or involuted thymus, early or late onset of the disease (which may follow different pathogenic mechanisms), or even non-MG patients." (PMID 36830985, 2023). "Most patients were positive for AChR Abs associated with titin Abs, RyR1 Abs associated with thymomas, and negative for MSAs." (PMID 37781409, 2023). "Therefore, positive testing for titin Abs in MG patients should be followed by comprehensive assessment for thymoma, particularly in patients under 50 years of age." (PMID 37887300, 2023). "Therefore, evidence demonstrates that anti-titin antibodies are a very useful biomarker for MG diagnosis and prognosis, especially for thymoma diagnosis." (PMID 36830985, 2023). "The identified much smaller titin antigenic region should lead to easier antigen production and thus less expensive diagnostics, to lower non-specific binding, i.e., more specific diagnostics, and should facilitate research on the relation of anti-titin antibodies with thymoma and with MG induction." (PMID 36830985, 2023). "In addition, the rate of patients who received systemic chemotherapy was higher in the titin+ group (38.7%) than in the titin– group (6.1%, p = 0.002), as the proportion of patients who experienced thymoma recurrence (32.2 vs. 9.1%, p = 0.030)." (PMID 36277908, 2022). "Furthermore, AChR+Titin-MG shows a shorter conversion time from ocular to generalized MG, a higher incidence of thymoma, and has a more severe presentation than AChR+LRP4-MG." (PMID 35614931, 2022). "We report a 77-year-old woman with a thymoma, anti-LGI1antibody associated encephalitis (LGI1 encephalitis), and MG accompanied by positive anti-acetylcholine receptor antibodies (AchR Ab) and anti-titin antibodies (titin Ab)." (PMID 35295746, 2022). "This may implicate that the patients with both the thymoma and anti-titin antibody are likely to be uncontrolled or experience more frequent relapses, which are severe enough to require hospitalization or ER visit." (PMID 36277908, 2022). "With regard to other MG patients, 43% (13/30) of those with late-onset and 40% (12/30) of those with thymoma-associated, but none of those with early-onset MG had anti-titin antibodies." (PMID 30918333, 2019). "Titin-Abs are variably used in patients with myasthenia gravis (MG) as biomarker of thymoma." (PMID 32010046, 2019). "Titin and RyR antibodies are found in 95% of thymoma MG, and 50% of late-onset MG (MG-onset > 50 years) are associated with severe disease and may predict thymoma MG outcome." (PMID 22312479, 2011). "About 95% and 70% of thymoma MG patients have titin and RyR antibodies, respectively." (PMID 21860784, 2011).
thymoma (continued). "Similarly, anti-titin Abs were detected in cases triggered by ICIs in which myasthenia and myositis overlap, suggesting a possible pathophysiological similarity between ICI-induced and thymoma-associated autoimmunity." (PMID 40181971, 2025). "While these antibodies have been infrequently reported in irMG, emerging evidence suggests that titin antibodies may serve as biomarkers for predicting immune-related adverse effects (irAEs), including irMG in the absence of an underlying thymoma." (PMID 40062097, 2025). "Furthermore, studies indicate that the PTPN22 T allele polymorphism is associated with non-thymoma MG in the absence of anti-titin antibodies." (PMID 40565966, 2025). "However, anti-titin and anti-RyR antibodies are present in most patients with thymoma." (PMID 39555481, 2024). "We evaluated whether the patients with anti-titin antibody are more frequently hospitalized to manage thymoma-associated MG than those patients without anti-titin antibody." (PMID 36277908, 2022). "In this study, we hypothesized that the patients with thymoma-associated MG having anti-titin antibody may experience more frequent worsening with greater severity than those without anti-titin antibody." (PMID 36277908, 2022). "Antibodies in thymoma combined with autoimmune encephalitis patients also involve anti‐GABAB, GAD65, NMDA, Ma2, Titin, and Hu." (PMID 36914970, 2023). "In addition, the patients with thymoma-associated MG with anti-titin antibody were more likely to use IVIg and tended to use oral immunosuppressive agents more frequently than the patients without anti-titin antibody." (PMID 36277908, 2022). "AChR antibody positive patients who also have titin or RyR antibodies tend to have more severe disease, while in the case of EOMG they are indicative of thymoma." (PMID 32117321, 2020). "The 3D structure of the titin MIR will help future studies on the pathomechamisms acting in titin-based autoimmunity and should also improve diagnostics for titin antibodies as an important biomarker for thymoma and MG severity diagnosis." (PMID 36830985, 2023). "A slight, but not significant reduction in the TTN mRNA levels was also observed in the MG B3/B3 mixed thymoma subtype compared to the same subtype in non-MG thymomas." (PMID 36979710, 2023). "As observed for RYR1, the type A/AB subset showed lower TTN mRNA levels in MG compared to non-MG thymomas, but the differences were not statistically significant." (PMID 36979710, 2023). "As described already, anti-titin antibodies are found in early onset MG with thymoma and in late-onset MG independent of thymoma presence; therefore, so far, measurement of anti-titin antibodies is useful only for early-onset MG patients." (PMID 36830985, 2023). "Autoantibodies to the intra-sarcomeric striated muscle-specific gigantic protein titin, although not directed to the NJ, are invaluable biomarkers for thymoma and MG disease severity." (PMID 36830985, 2023). "Transcriptional levels of CHRNA1, RYR1, and TTN autoantigen genes were assessed in hyperplastic and thymoma thymuses of MG patients, non-MG thymomas, and normal thymuses using real-time PCR." (PMID 36979710, 2023). "Anti-AChR, anti-RYR1, and anti-TTN antibodies were tested in 13 available sera from non-MG thymoma patients, including 7 patients with type A/AB, 5 patients with type B1/B2, and 1 patient with type B3/B3 mixed thymoma." (PMID 36979710, 2023). "No thymomas were detected, and the anti-titin Ab test showed a consistent result (negative in 100%)." (PMID 35246057, 2022). "Those against the muscle have been attributed to the lack of thymic myoid cells (TMCs) in thymomas and/or expression of AChR, titin and RYR epitopes in neoplastic thymic epithelial cells." (PMID 33537838, 2021). "Unlike in EOMG, >80% of patients with thymomas have autoantibodies to non-AChR skeletal muscle antigens (titin and RYRs) and others that neutralise such cytokines as type I interferons (~70% and IL-12)." (PMID 33537838, 2021).
thymoma (continued). "These low titin antibody titers did not correlate with the presence of thymoma, in accordance with previous findings that thymoma is unlikely in MG patients without AChR antibodies." (PMID 33329350, 2020). "Striated muscle antibodies against muscle cytoplasmic proteins (titin, myosin, actin, and ryanodine receptors) are detected mainly in patients with thymomatous MG and also in some thymoma patients without MG." (PMID 23193443, 2012). "The presence of titin and RyR antibodies in an MG patient younger than 60 years strongly suggests a thymoma, while their absence at any age strongly excludes thymoma." (PMID 21860784, 2011). "In contrast to this model, we report here that titin, which is a recentlyreported target of SA autoimmunity, is not expressed in thymomas." (PMID 1379503, 1992). "The lack of TMCs in thymoma and/or the expression of AChR, titin, and RyR epitopes in neoplastic TECs may also account for the generation of muscle Abs." (PMID 41164186, 2025). "To further address the question whether the intra-thymic expression of muscle autoantigens is altered in AChR-MG patients, we searched for possible changes in the CHRNA1, RYR1, and TTN expression levels, in relationship with AIRE expression, in hyperplastic MG thymuses and MG thymomas." (PMID 36979710, 2023). "Specifically, for early-onset MG, the presence of anti-titin antibodies strongly indicates thymoma, as 50–95% of early-onset (<40–50 years old) MG patients with thymoma are anti-titin positive, and only a few non-thymomatous early-onset MG patients are found anti-titin positive." (PMID 36830985, 2023). "Microarrays data from Radovich and colleagues demonstrated that the transcriptional levels of the medium-sized neurofilament, NEFM, which exhibit immunogenic similarities with AChR-α and TTN, were higher in MG compared to non-MG thymomas, and even higher in the MG A/AB subset." (PMID 36979710, 2023). "For the rare thymomas without thymopoiesis and AChR/Titin expression, alternative pathogenetic models may apply." (PMID 33537838, 2021). "In total, three cases were positive for Titin antibody, including two elderly patients and one middle-aged male patient, suggesting that the patients may be accompanied by thymoma, but it has not been confirmed by imaging and pathology." (PMID 34956185, 2021). "Low titer titin antibodies found in SNMG did not correlate with the presence of thymoma." (PMID 32117321, 2020). "Titin antibodies and other striated muscle antibodies are also found in up to 50% of patients with late-onset and nonthymomatous MG and are less helpful as predictors of thymoma in patients over 50 years." (PMID 23193443, 2012). "Moreover, they are found in thymoma patients without MG, suggesting that the occurrence of thymoma in itself could alter titin presentation to T cells." (PMID 36800019, 2023). "However, the presence of titin and RyR antibodies in a MG patient younger than 60 years strongly suggests a thymoma, while the absence of such antibodies at any age strongly excludes thymoma." (PMID 21860784, 2011). "One patient with type A/AB thymoma, who was negative for anti-AChR antibodies, was positive for both anti-RYR1 and anti-TTN antibodies; the remaining non-MG thymoma patients were negative for autoantibodies." (PMID 36979710, 2023). "We found that CHRNA1 (AChR-α subunit) and AIRE (autoimmune regulator) genes were expressed at lower levels in hyperplastic and thymoma MG compared to the control thymuses, and that the RYR1 and TTN levels were decreased in MG versus the non-MG thymomas." (PMID 36979710, 2023). "Similarly to CHRNA1, genes encoding for the two thymoma-associated autoantigens RYR1 and TTN were expressed at lower levels in MG compared to non-MG thymomas, with RYR1 being mainly down-regulated in the MG A/AB subset, and TTN in the MG A/AB and B3/B3 mixed subset." (PMID 36979710, 2023).
muscular dystrophy (37 papers, 2005 to 2025). Muscular dystrophy (MD) refers to a group of more than 30 genetic diseases characterized by progressive weakness and degeneration of the skeletal muscles that control movement. "TTN gene and the protein encoded by it are large and therefore more susceptible to mutations and related to muscle weakness, heart disease, muscular dystrophy, and breast cancer." (PMID 36982287, 2023). "Muscular dystrophy with myositis (mdm) is one such titin-associated disease in mice, and caused by a complex rearrangement at the N2A-PEVK region of titin, that disrupts one of the most important active sites for titin-based force regulation." (PMID 36115951, 2022). "The significance of calpain-3’s interaction with titin was investigated in mice with muscular dystrophy with myositis (mdm) that showed an abrogation of calpain-3’s association with titin in addition to severe pathological phenotypes." (PMID 34299183, 2021). "Mutations in titin proteins result in the weakening of muscle and are responsible for heart disease and muscular dystrophy." (PMID 32731431, 2020). "Titin is the most extensively studied of the M-line proteins and mutations in titin’s C-terminus lead to limb girdle muscular dystrophies, tibial and Salih congenital muscular dystrophies." (PMID 31644553, 2019). "Mutations in the C-terminal M10 domain of titin, which binds the Ig1 of obscurin, cause Tibial Muscular Dystrophy (TMD) or Udd myopathy in the heterozygous state, and Limb Girdle Muscular Distrophy 2J in the homozygous state." (PMID 29073160, 2017). "Mutations in mouse titin genes cause muscular dystrophy, cardiac development defects and muscle weakness." (PMID 16242019, 2005). "TTN is a protein-coding gene associated with myopathy and muscular dystrophy." (PMID 38977697, 2024). "Mutations in TTN are a known cause for several muscular dystrophies including limb-girdle muscular dystrophy (LGMD) and has many alternatively spliced isoforms with distinct functions, suggesting that splicing alteration of this gene can be associated with muscular pathology." (PMID 38809976, 2024). "Indeed, biochemical analyses of the various titin mutations found in titin Ig-domain M10 indicated that the severity of the muscular dystrophy correlates with the degree of loss of interaction to obscurin or Obsl1." (PMID 31098411, 2019). "Further experiments to investigate the relationship of muscular dystrophy phenotypes to fluctuation of CK activity and titin fragment levels in long term in DMD-null mice would be beneficial." (PMID 39805937, 2025). "Previous studies have reported cases with concurrent TTN and LAMA2 mutations, highlighting overlapping features of muscular dystrophy." (PMID 39926328, 2025). "Consistent implication of MYBPC3, CSRP3, CAV3, TCAP, and TTN across multiple pathways highlights convergent mechanisms, while moderate enrichment of muscular dystrophy pathways (involving CAV3 and TTN) further suggests overlapping pathophysiological networks." (PMID 41153379, 2025). "The N-terminal titin fragment (N-titin) is released in urine and has been detected in several muscular dystrophies." (PMID 39456682, 2024). "These two genes, DMD and TTN, are the most significant differentially expressed genes (DEGs) that contribute to the development of muscular dystrophy." (PMID 39415830, 2024). "Muscular dystrophy with myositis (mdm) is an important mouse model to study titin function in skeletal muscles as it affects a key active stiffness modulator in activated muscles." (PMID 36115951, 2022). "The muscular dystrophy with myositis mice (mdm) is by far the most studied titin animal model, widely used to characterize titin physiology in skeletal muscle." (PMID 36065969, 2022). "Mutations in TTN and LDB3 genes can cause the abnormal development of the skeletal muscle, leading to muscular dystrophy." (PMID 34698087, 2021).